BGLAP (bone gamma-carboxyglutamate protein)
Description:
The carboxylated form is one of the main organic components of the bone matrix, which constitutes 1-2% of the total bone protein. Acts as a negative regulator of bone formation and is required to limit bone formation without impairing bone resorption or mineralization (By similarity). Binds strongly to apatite and calcium upon gamma-carboxylation; this modification is essential for bone metabolism. The uncarboxylated form acts as a hormone secreted by osteoblasts, which regulates different cellular processes, such as energy metabolism, male fertility and brain development. Regulates of energy metabolism by acting as a hormone favoring pancreatic beta-cell proliferation, insulin secretion and sensitivity and energy expenditure. Uncarboxylated osteocalcin hormone also promotes testosterone production in the testes: acts as a ligand for G protein-coupled receptor GPRC6A at the surface of Leydig cells, initiating a signaling response that promotes the expression of enzymes required for testosterone synthesis in a CREB-dependent manner. Also acts as a regulator of brain development: osteocalcin hormone crosses the blood-brain barrier and acts as a ligand for GPR158 on neurons, initiating a signaling response that prevents neuronal apoptosis in the hippocampus, favors the synthesis of all monoamine neurotransmitters and inhibits that of gamma-aminobutyric acid (GABA). Osteocalcin also crosses the placenta during pregnancy and maternal osteocalcin is required for fetal brain development.
Synonyms: BGP; OCN; OC
Tractability: Small molecule: a structure with a bound ligand is known. Antibody: UniProt places it where antibodies can reach, with high confidence; UniProt predicts a signal peptide or a membrane-spanning region; its Gene Ontology location is reachable by antibodies, with medium confidence.
Safety:
Unwanted effects reported when the protein is acted on. In parentheses: how it was acted on, where the effect was seen, and who reports it.
Impaired recruitment , Population trajectory (source: AOP-Wiki)
Gene: Protein-coding gene on chromosome 1 (156,242,184 to 156,243,317, forward strand). Ensembl gene ENSG00000242252.
Subcellular location: Secreted
Pathways (Reactome):
Metabolism of proteins: Gamma-carboxylation of protein precursors; Removal of aminoterminal propeptides from gamma-carboxylated proteins; Transport of gamma-carboxylated protein precursors from the endoplasmic reticulum to the Golgi apparatus
Gene expression (Transcription): RUNX2 regulates osteoblast differentiation
Gene Ontology:
Molecular function: protein binding; hormone activity; hydroxyapatite binding; structural constituent of bone; structural molecule activity; calcium ion binding
Biological process: osteoblast differentiation; response to vitamin D; bone development; bone mineralization; brain development; cell adhesion; cellular response to insulin stimulus; cognition; glucose homeostasis; learning or memory; negative regulation of bone development; positive regulation of neurotransmitter secretion; regulation of bone resorption; regulation of osteoclast differentiation; regulation of testosterone biosynthetic process; skeletal system development; type B pancreatic cell proliferation; cellular response to growth factor stimulus; cellular response to vitamin D; cellular response to zinc ion starvation; ossification; regulation of bone mineralization; regulation of cellular response to insulin stimulus; response to activity; response to estrogen; and 15 more
Cellular component: cytoplasm; extracellular region; endoplasmic reticulum lumen; Golgi lumen; non-collagenous component of interstitial matrix; dendrite; perikaryon; vesicle
Genetic constraint (gnomAD): Loss-of-function variants: 15 observed, 12.27 expected, observed/expected ratio (o/e) 1.22, 90% interval 0.81 to 1.79. The upper end of that interval is the gene's LOEUF score, 1.79, which puts it in group 6 of 6, group 1 being the genes least tolerant of losing a copy. Missense variants: 120 observed, 130.91 expected, observed/expected ratio (o/e) 0.92, 90% interval 0.79 to 1.07. Synonymous variants: 67 observed, 57.48 expected, observed/expected ratio (o/e) 1.17, 90% interval 0.96 to 1.43.
Homologues: Orthologues: chimpanzee BGLAP (99% identical), pig BGLAP (86% identical), dog BGLAP (81% identical), rabbit BGLAP (80% identical), guinea pig BGLAP (78% identical), rat Bglap (71% identical), chimpanzee BGLAP (68% identical), mouse Bglap2 (63% identical), mouse Bglap (61% identical), mouse Bglap3 (60% identical), zebrafish bglap (32% identical).